PDC (phosducin)
Description:
May participate in the regulation of visual phototransduction or in the integration of photoreceptor metabolism. Inhibits the transcriptional activation activity of the cone-rod homeobox CRX.
Synonyms: PHD; MEKA; PhLOP; PhLP
Tractability: No criterion of Open Targets' tractability assessment is met for any kind of drug.
Gene: Protein-coding gene on chromosome 1 (186,443,566 to 186,461,114, reverse strand). Ensembl gene ENSG00000116703.
Subcellular location: Cytoplasm, cytosol; Nucleus; Cell projection, cilium, photoreceptor outer segment; Photoreceptor inner segment; Nucleus (Isoform 2)
Gene Ontology:
Molecular function: phospholipase inhibitor activity
Biological process: G protein-coupled receptor signaling pathway; phototransduction; regulation of G protein-coupled receptor signaling pathway
Cellular component: nucleus; photoreceptor outer segment; cytosol; photoreceptor inner segment
Genetic constraint (gnomAD): Loss-of-function variants: 8 observed, 7.16 expected, observed/expected ratio (o/e) 1.12, 90% interval 0.65 to 1.81. That is too few expected variants to judge how well the gene tolerates losing a copy. Missense variants: 147 observed, 159.25 expected, observed/expected ratio (o/e) 0.92, 90% interval 0.81 to 1.06. Synonymous variants: 54 observed, 57.61 expected, observed/expected ratio (o/e) 0.94, 90% interval 0.75 to 1.18.
Homologues: Orthologues: chimpanzee PDC (99% identical), macaque PDC (98% identical), dog PDC (90% identical), pig PDC (89% identical), guinea pig PDC (89% identical), rabbit PDC (89% identical), mouse Pdc (88% identical), rat Pdc (88% identical), tropical clawed frog pdc (64% identical), zebrafish pdca (61% identical), zebrafish pdcb (59% identical), Drosophila melanogaster CG7650 (32% identical), and 1 more. Paralogues in human: PDCL (47% identical), PDCL3 (24% identical), PDCL2 (21% identical), TXNDC9 (15% identical).
Diseases named in the same sentence as PDC in open-access papers:
PDC is named in the same sentence as 132 diseases in open-access papers, as found by Europe PMC text mining. Sharing a sentence is not in itself a finding about the gene and the disease. The quoted sentences say what the papers report.
viral infection (51 papers, 2008 to 2025). "pDC infiltrate human skin lesions and produce type I IFNs during virus infections caused by Molluscum contagiosum virus (MCV) and Varicella zoster virus." (PMID 32903701, 2020). "We thus reasoned that the attenuated IFN production and associated increased viral infection observed in RAGE deficient mice would be associated with defective pDC recruitment." (PMID 28099113, 2017). "We evaluated the contribution of pDCs to acute and chronic virus infection using the feeble mouse model of pDC functional deficiency." (PMID 23028315, 2012). "This implies that LC-Plasma can potentially facilitate pDC maturation and could be particularly beneficial for the elderly, as they are known to have lower pDC counts and are more susceptible to viral infections." (PMID 39597693, 2024). "Since the association of pDC with viral infections, maybe we can associate pDC with HBV in HCC through TSPAN9." (PMID 35600044, 2022). "To assess whether pDC activation requires virus infection, as has been described for some viruses, we first investigated whether pDC are susceptible to PRV infection." (PMID 34843605, 2021). "In addition, vaginal SIV infection rapidly induces a local inflammatory response with pronounced type I IFN production, and similar responses occurring subsequent to mucosal viral infection in the mouse are associated with pDC recruitment and activation that suppresses virus replication." (PMID 19424421, 2009). "Our work thus identifies a mechanism for balancing immunity and pathology during viral infections, while also providing insight into the highly preserved infection-driven pDC inhibition." (PMID 39920132, 2025). "This suggests that LDHB expression and pDC inhibition manage a trade-off between supporting pDC function and opposing host-pathology during viral infection." (PMID 39920132, 2025). "Based on the results of the culture study and previous reports, HC administration may have induced pDC activation in vivo, leading to early and strong induction of immune responses, such as NK cell activation and increased sIgA levels associated with IFNα upregulation at the time of viral infection." (PMID 38957464, 2024). "It will also be of interest to investigate the mechanism and role of this pathway of pDC and macrophage activation in other viral infections." (PMID 37253946, 2023). "pDC is first recognized as an important regulator of the immune response to virus infection because of its capacity of producing large amounts of IFN-α51." (PMID 36635346, 2023). "It has been also demonstrated that, in response to viral infection or single stimuli, pDC undergo phenotypical diversification." (PMID 34209845, 2021). "During viral infections, the functions of pDC are crucial as they are the main producer of the antiviral cytokine type I IFN." (PMID 34209845, 2021). "To assess the impact of pDC activation on global TF expression in these cells, we simulated early events after virus infection in a time course study." (PMID 34544361, 2021). "pDC are classified as the major type I IFN producing cells following viral infections by sensing viral RNAs via TLR7." (PMID 34473805, 2021). "Consistently, pDC are responsible for ~50% of all circulating IFN-I during acute viral infections despite being extremely rare cells." (PMID 30262916, 2018). "Since pDC were reported to play antiviral functions and that 70% of the causes of URTI were viral infections, we can conclude that LC-Plasma supplementation relieves URTI morbidity during HIE via pDC activation." (PMID 30071871, 2018). "The propagated importance of pDC for early sensing of viral infection is supported by the high transcription rate of TLR3, TLR7, and TLR9 found in bovine pDC." (PMID 30425716, 2018). "SLC15A4, selectively transcribed in bovine and also in human pDC, was shown to be required for signaling through TLR7 and TLR9 in murine pDC and, as a consequence, for pDC-mediated control of persistent viral infection." (PMID 30425716, 2018).
viral infection (continued). "Transgenic mouse models have been designed to allow conditional depletion of pDC during virus infections, demonstrating the important role of pDC in mediating early antiviral IFN responses." (PMID 29118754, 2017). "During viral infections in mice, the impact of MyD88 inactivation or pDC depletion had only been assessed on the basis of IFN-I production." (PMID 25954804, 2015). "The contribution of pDC to the early innate control of viral infections was shown to be critical against rapidly replicating viruses such as Herpes simplex virus, respiratory syncytial virus, mouse cytomegalovirus, and vesicular stomatitis virus (VSV)." (PMID 24816846, 2014). "Taken together this work illustrates how the cytokine network can influence pDC activation, a knowledge of relevance for improving vaccines and therapeutic interventions during virus infections, cancers and autoimmune diseases in which pDC play a role." (PMID 23577175, 2013). "Recently, reduced pDC numbers were found to underlie decreased immunity in advanced age and that in late aged mice (18–26 months), pDC are reduced in their ability to produce IFNa in response to viral infection." (PMID 21695169, 2011). "pDC are thought to be particularly important in immune responses against viral infections, including HIV." (PMID 19936055, 2009). "Our observation that pDC depletion occurs in HIV-2 infected patients with undetectable viremia indicates that mechanisms other than direct viral infection determine the pDC depletion during persistent infections." (PMID 19936055, 2009). "This decrease was observed early in disease and also in HIV-2 infected patients with undetectable viremia, suggesting that mechanisms other than pDC direct viral infection play major roles in their depletion during persistent infections." (PMID 19936055, 2009). "Given that pDC-mediated responses to viral infections usually require physical contact with infected cells (16, –, 18), we asked whether direct contact between pDCs and SARS-CoV-2-infected cells was necessary for efficient IFN-I production." (PMID 39804090, 2025). "Indeed, as shown in vitro, pDC IFN production during viral infections in vivo is driven by TLR7/9-dependent endosomal recognition of engulfed viral nucleic acids." (PMID 38777879, 2024). "This was interpreted as proof of defective pDC-dependent control of viral infection in these patients, which could be responsible for their life-threatening susceptibility to COVID-19." (PMID 38777879, 2024). "More studies are needed to understand this complexity and precisely identify the underlying mechanisms controlling pDC activation for IFN-I production in nonlymphoid barrier tissues during peripheral viral infections." (PMID 38777879, 2024). "As evidence supporting the persistent viral infection, in addition to long-term pDC deficient, reductions in non-classical monocytes and a subset of natural killer cells have been observed in the MIS-C group." (PMID 35813874, 2022). "In pDC, glycolysis could be induced by virus infection and that regulate pDC antiviral functions, including IFN-α production and phenotypic maturation." (PMID 32208814, 2020). "The pDC plays an important role in providing type 1 IFN in response to ssRNA virus infection." (PMID 28265274, 2017). "Indeed, in murine models of virus infection ablation of pDC impacts IFN-α production only in the very early stages after infection, up to 36 hours; non-pDC are responsible for IFN-α at later time points." (PMID 23935491, 2013). "Recently, hepatitis B surface antigen (HbsAg) has also been shown to ligate BDCA-2, suggesting that inhibition of pDC responses may be an important factor in a variety of viral infections." (PMID 22693567, 2012). "Firstly, the results verify the importance of pDC during viral infections for promoting the appropriate and non-pathogenic responses." (PMID 18320041, 2008).
viral infection (continued). "However, it is possible that pDC inhibition emerges after transient IFN-I production (as in the viral infection), and that de novo generated pDCs may continuously provide a new source of IFN-I prior to becoming suppressed." (PMID 39920132, 2025). "All together these data provide a resource of gene expression data for pDC peak IFN-I response and subsequent pDC suppression during a natural viral infection, including the first defined pDC exhaustion signature, which may be useful for the identification of pDC regulators in future studies." (PMID 39920132, 2025). "In addition to IFNs, pDC are also able to rapidly produce pro-inflammatory cytokines and chemokines upon viral infection; therefore we analyzed the secretion of the pro-inflammatory cytokines IL-6, TNF, and the chemokine IL-8 protein in the cell culture supernatants by ELISA." (PMID 30344524, 2018). "Thus, pDC numbers are tightly regulated during viral infections." (PMID 28225814, 2017). "However, the pDC function depends on the etiology of viral infection." (PMID 23755314, 2013). "The protective effects of LC-Plasma activation of pDC, which in turn, induced IFN-α, however, have been widely observed in multiple earlier studies on viral infections." (PMID 34960061, 2021). "Consistent with previous observations, stimulation with infectious VSV-M2 triggered mainly the pDC to produce large amounts of IFN-α, confirming the role of pDC as the main IFN producing cells after viral infection." (PMID 27385030, 2016). "In response to viral infection, pDC further increase IFN production via TLR7 and TLR9 pathways, leading to increased pDC migration and maturation." (PMID 19830165, 2009). "However, pDC activation during viral infections appears to be tightly controlled in intensity, space, and time, by a variety of mechanisms, which may be in place to tune the risk of cytokine shock to the level of threat posed to a specific host by a given viral infection." (PMID 21994554, 2009). "Although the vast majority of studies analyzing pDC functions have focused on their role in IFN production and the induction of protective intrinsic, innate, or adaptive immunity during viral infections, it is important to realize that pDCs are already very active under homeostatic conditions." (PMID 38777879, 2024). "Type I IFNs are the most potent antiviral cytokines known in nature and the absence of pDC or type I IFNs has been shown to critically affect the outcome of virus infection, particularly alphaherpesviruses, including HSV or VZV." (PMID 34843605, 2021). "This metabolic pathway was shown to regulate pDC antiviral functions, including IFN-α production and phenotypic maturation, demonstrating for the first time the unrecognized role for metabolism in regulating pDC immune responses to viral infections in humans." (PMID 27211546, 2016). "From this we conclude that viral infection or viral products were responsible for the pDC reduction, but it was unlikely to be mediated by the host’s type I IFN response." (PMID 26624012, 2015). "In this report we studied pDC activation by DENV and its consequences on viral infection." (PMID 23755314, 2013). "Previous studies concluding a major role for pDC in controlling local viral infections, such as HSV, may have been a consequence of depleting other cell types in addition to pDC." (PMID 24204273, 2013). "Although pDC activation is usually induced by the recognition of viral DNA or RNA during viral infection, agents that activate pDCs can be used to enhance the host’s defense system without viral infection." (PMID 37892533, 2023). "As with inhibitory receptors the functions of most of these soluble molecules are primarily established in vitro or ex vivo and the roles these factors play and the mechanisms by which they modulate pDC function during viral infection in vivo are not fully elucidated." (PMID 34578420, 2021).
viral infection (continued). "Thus, our study provides important evidence on the direct and critical role of local pDC in the protection of a non-lymphoid tissue from viral infection." (PMID 32877681, 2020). "Similarly, it may also explain why treatments inducing pDC recruitment and a strong type I IFN response before vaginal challenge in macaques are incapable of limiting viral infection beyond the infected mucosa and can even enhance viral replication." (PMID 31114569, 2019). "Indeed, for other viruses it was shown that direct virus infection of pDC was not required to trigger IFN-α responses." (PMID 30075026, 2018). "Indeed, with several other viral infections, including infections with the herpesviruses HSV-1 and HSV-2, pDC were shown to contribute to IFN-I production only under condition of systemic viral spread and not under conditions where the infections is performed and controlled in epithelia." (PMID 25954804, 2015). "In addition, the red gene signature includes TLR2, TLR4, and TLR8, which are not prominent pDC receptors but may play a role in pDC activation under specific conditions, such as during viral infection or in inflamed tissues." (PMID 31552042, 2019).
lupus (39 papers, 2008 to 2025). "These discoveries explain the causative effect of dysfunctional NCF1 in lupus and demonstrate the protective role of pDC-derived ROS in disease development driven by NCF1-dependent ROS deficiency." (PMID 36853827, 2023). "ERα deficiency reduced the TLR9-dependent expression of PDC-TREM in pDCs from mice of NZM2410 (lupus-prone) or C57BL/6 genetic background." (PMID 28239379, 2017). "In marked contrast, TLR9-deficient lupus-prone mice exhibit more severe lupus and activated pDC, which concords with our previous findings that TLR9 and CpG DNA is linked to protection from autoimmunity." (PMID 18997868, 2008). "However, in vivo experiments showed the increased pDC expansion in cGAS-deficient mice, which hints to us to investigate the underlying mechanism of these findings that’s more complex in pristane-induced lupus than in vitro." (PMID 36591278, 2022). "There is a shift in the signaling sources of the PARs pathway, with cDC as the signal source in Mpj mice, and pDC in Lpr mice, where pDC cells are the primary immune cells responsible for type I interferon production in lupus pathogenesis." (PMID 39871323, 2025). "A feature of lupus lesions from VISTA KO mice is pDC clustering, and neutrophils infiltrate the skin before clinically evident disease, and subsequently develop more severe systemic lupus erythematosus and inflammatory arthritis." (PMID 37435070, 2023). "First, the IMQ-induced lupus model used in our study was pDC dependent, and antibody-mediated clearance of pDCs in vivo hampered the occurrence of lupus." (PMID 35788118, 2022). "Currently, a potential relationship between TLR7 stimulation and lupus-like disease development in the imiquimod (IMQ)-induced lupus model is unclear, other than the mechanism involving pDC." (PMID 35371102, 2022). "pDCs are a major source of IFN-α, and lupus-prone mice with defective pDC-mediated IFN response have reduced autoantibody formation, reduced lymphadenopathy, and prolonged survival." (PMID 34554930, 2021). "Novel reagents inhibiting pDC activity have shown promise in clinical trials in reducing the severity of symptoms in lupus." (PMID 34181694, 2021). "This unique transgenic mouse model has been successfully used to investigate the pDC functions in viral and bacterial infections, and in systemic lupus erythematosus (SLE) model." (PMID 32054102, 2020). "The depletion of pDC ameliorates the autoimmune phenotypes in BXSB lupus-prone mice and B6.Nba2 mice." (PMID 33083760, 2020). "Diphtheria toxin receptor (DTR)‐based transient depletion of pDC in lupus‐prone mice before disease onset resulted in amelioration of disease." (PMID 32489664, 2020). "Blood dendritic cell antigen 2 (BDCA2), a pDC specific receptor, has been targeted for preclinical and clinical investigation of lupus treatment." (PMID 31921124, 2019). "pDC depletion in lupus-prone mice prior to disease initiation resulted in reduction in autoimmune pathology." (PMID 31921124, 2019). "Other than TLRs and proteins implicated in their intracellular trafficking, a recent study pointed to ERα-dependent regulation of the cell surface molecule PDC-triggering receptor expressed on myeloid cells (TREM) in pDCs from lupus-prone mice." (PMID 28239379, 2017). "Aberrant pDC function has been shown to be involved in psoriasis, systemic lupus erythematosus (SLE), and rheumatoid arthritis (RA)." (PMID 29085361, 2017). "In this review, we summarize recent results obtained from studies of SLE patients and lupus-prone mice on the roles of cDC and pDC in lupus development." (PMID 27034965, 2016). "Due to the critical role of pDC and IFNα in the development of lupus, potential treatment strategies targeting them have been proposed." (PMID 27034965, 2016). "Due to the critical role of IFNα in lupus development, how pDC are activated to produce IFNα in lupus has been studied." (PMID 27034965, 2016).